IKBKG (inhibitor of nuclear factor kappa B kinase regulatory subunit gamma)
Diseases named in the same sentence as IKBKG in open-access papers (continued):
Sharing a sentence is not in itself a finding about the gene and the disease.
Immunodeficiency (continued). "This method should be modifiable for other gene/pseudogene combinations which inhibit standard sequencing diagnosis such as IKBKG/NEMO deficiency, associated with immune deficiency with or without ectodermal dysplasia." (PMID 40934010, 2025). "Hypomorphic hemizygous missense variants or short truncations of IKBKG in males that impair but do not abolish NF-kB signaling lead to hypohidrotic ectodermal dysplasia with immunodeficiency (EDA-ID, OMIM#300291) as well as immunodeficiency without EDA." (PMID 39860371, 2025). "Of notice, IKBKG is involved in immune regulation, and single case reports suggest that patients with IP have a risk of immunodeficiency with impaired NF-kappa-B signaling due to non-skewed X-inactivation." (PMID 39623400, 2024). "Through the ability of long-read sequencing to unambiguously call variants in these regions, we discovered an immunodeficiency due to a variant in IKBKG in a subject who had previously received a negative genome sequencing result." (PMID 36210382, 2022). "Hypomorphic hemizygous IKBKG disease-causing variants are typically associated with immunodeficiency with or without anhidrotic ectodermal dysplasia." (PMID 36210382, 2022). "However, of the four immunodeficiency phenotype cases that underwent LRS, a maternally-inherited stop-loss variant (p.X420Yext27; VCV00011450) in IKBKG (inhibitor of nuclear factor kappa-b kinase, regulatory subunit gamma) was identified in one proband." (PMID 36210382, 2022). "Immunodeficiency is a frequent but not invariable feature of hypomorphic IKBKG mutations." (PMID 36733767, 2022). "Osteopetrosis caused by mutations of the IKBKG (inhibitor of nuclear factor kappa B kinase subunit gamma) gene, located on the X chromosome, occurs as a moderate complication of the OL-EDA-ID syndrome, lymphedema, anhidrotic ectodermal dysplasia and immunodeficiency (hence, the acronym)." (PMID 30837952, 2019). "Here, we report the case of an IKBKG female carrier, with no IP but an unexpected picture of immunodeficiency." (PMID 39860371, 2025).
ectodermal dysplasia (31 papers, 2012 to 2025). "As a downstream regulator within this pathway, IKBKG mutations can also induce ectodermal dysplasia, particularly affecting tooth tip formation." (PMID 40612668, 2025). "The IKBKG gene is found mutated in hypohidrotic ectodermal dysplasia, accompanied by variable degrees of alopecia." (PMID 35413801, 2022). "In conclusion, we have identified a nonsense variant in the equine IKBKG gene as most likely causative for a hereditary ectodermal dysplasia in horses." (PMID 24324710, 2013). "The IKBKG protein serves as an example, which was only associated with ectodermal dysplasia (OMIM #300301) in the literature." (PMID 23921638, 2013). "X-linked hypohidrotic ectodermal dysplasia results from hypomorphic variants in the IKBKG gene and affected individuals suffer from recurrent severe infections in addition to the symptoms due to ectodermal dysplasia including the classical triad of hypohidrosis, hypodontia and hypotrichosis." (PMID 36839544, 2023). "Dental abnormalities are hallmark features of ectodermal dysplasia, with tooth anomalies being the predominant developmental irregularity observed in EDA-ID associated with IKBKG mutations." (PMID 40612668, 2025). "Because the physiological process of ectodermal development relies on the regulatory factor NEMO in the NF-κB pathway, mutations in IKBKG can result in significant ectodermal dysplasia manifestations." (PMID 40612668, 2025).
colitis (30 papers, 2009 to 2025). Inflammation of the colon. "The global survival rate after hematopoietic stem-cell transplantation among IKBKG-deficient children was 74% at a median follow-up after hematopoietic stem-cell transplantation of 57 months, and most of the clinical symptoms caused by IKBKG mutation were curable, except for colitis." (PMID 40612668, 2025). "P1 (IKBKG p.R63Q) suffered with Evans syndrome, colitis and granulomatous hepatitis." (PMID 28983403, 2017).
viral infection (27 papers, 2009 to 2025). "Other noticeable network clusters included NFATC1–GRAP2 (viral infection), IL6–S100A12 (neutrophil activation), and IKBKG (complement and B cell activation)." (PMID 39921901, 2025).
hepatocellular carcinoma (21 papers, 2009 to 2025). A malignant tumor that arises from hepatocytes. "The deletion of NEMO/IKBKG, an activation complex for NFKB, in liver parenchymal cells led to steatohepatitis and hepatocellular carcinoma." (PMID 31363162, 2019).
breast carcinoma (16 papers, 2014 to 2022). "IKBKG is significantly upregulated in inflammatory breast cancer (IBC) tumor samples in comparison to regular breast cancer tumor samples (non IBC), and it is more down-regulated in IBC metastases in comparison to that of non IBC." (PMID 35428183, 2022).
hypohidrotic ectodermal dysplasia (12 papers, 2012 to 2025). A genetic disorder of ectoderm development characterized by malformation of ectodermal structures such as skin, hair, teeth and sweat glands. "Hypohidrotic ectodermal dysplasia (HED) is an X-linked trait caused by hypomorphic mutation in the IKBKG (or EDA) gene, encoding nuclear factor κB essential modulator (NEMO)." (PMID 26239454, 2015).
osteopetrosis (12 papers, 2016 to 2025). Osteopetrosis, also known as marble bone disease, is a descriptive term that refers to a group of rare, heritable disorders of the skeleton characterized by increased bone density on radiographs. "Osteopetrosis can also present with an X-linked recessive inheritance pattern caused by a mutation in the IKBKG gene on the X chromosome." (PMID 29353820, 2018). "The X-linked form of osteopetrosis results from mutationsin the IKBKG gene." (PMID 37465191, 2023). "Furthermore, in two patients with the X420W mutation in the IKBKG gene showing mild osteopetrosis with substantial extramedullary hematopoiesis, osteoclasts were observed to remain in bone tissue sections." (PMID 35887342, 2022). "The AD, AR and XL forms of osteopetrosis are predominantly caused by mutations in the CLCN7, TCIRG1 and IKBKG genes respectively." (PMID 31888683, 2019). "IKBKG, LRP5, and TNFSF11 are mainly due to the interaction of osteoblasts and osteoclasts, which cause an imbalance between bone formation and bone absorption, resulting in osteopetrosis." (PMID 37373559, 2023).
COVID-19 (11 papers, 2021 to 2026). A disease caused by infection with severe acute respiratory syndrome coronavirus 2. "The proteins encoded by the ‘dark’ genes TRADD, FOS and DDGs RELB, JUN, IKBKG are involved in the MAPK signaling pathway, which is a potential signaling pathway for the spread and development of COVID-19." (PMID 37853311, 2023).
liver cancer (10 papers, 2014 to 2024). An epithelial or non-epithelial malignant neoplasm that arises from the liver. "To further investigate the clinical significance of IKBKG splicing in cancer patients, we examined the relative levels of two IKBKG isoforms in six pairs of liver cancer samples and adjacent normal tissues." (PMID 36225557, 2022). "In addition to liver cancer, we examined the splicing change of IKBKG upon melatonin treatment in NCI-H1299 and A549 lung cancer cells, and human embryonic kidney HEK-293T cells." (PMID 36225557, 2022).
autoinflammatory syndrome (8 papers, 2021 to 2025). A group of disorders of the innate immune system characterized by attacks of seemingly unprovoked inflammation without significant levels of either autoantibodies or autoreactive T cells more characteristic of autoimmune disease. "Here, we characterized a pediatric autoinflammatory syndrome in 3 unrelated male patients with distinct X-linked IKBKG germline mutations that led to overexpression of a NEMO protein isoform lacking the domain encoded by exon 5 (NEMO-Δex5)." (PMID 35289316, 2022).
inflammatory bowel disease (8 papers, 2009 to 2025). A spectrum of small and large bowel inflammatory diseases of unknown etiology. "Several IEC signature TFs have known associations with human Inflammatory Bowel Diseases (IBD), including SMAD7, CEBPG, STAT3, XBP1, HNF4A, ELF3, IRF1, and NFκB components IKBKB, IKBKG, and NFKBIZ." (PMID 28850571, 2017).
Behcet disease (5 papers, 2013 to 2025). A chronic, relapsing, multisystemic vasculitis characterized by mucocutaneous lesions, as well as articular, vascular, ocular and central nervous system manifestations. "Recently, IKBKG p.Asp406Val has also been reported in the context of Behçet syndrome, further underscoring the importance of the NF‐κB pathway in Behçet syndrome." (PMID 39964335, 2025).
colon carcinoma (5 papers, 2010 to 2025). "In colon cancer, lower IKBKB and IKBKG protein levels were noted in tumor tissue compared to normal tissue (p < 0.01; 0.036, respectively)." (PMID 39337357, 2024).
Hepatitis (5 papers, 2017 to 2024). Inflammation of the liver. "Patients with NDAS present with uveitis, a predominantly lymphohistiocytic panniculitis, hepatitis, and a striking lack of severe or recurrent infections, which distinguishes them from patients with other clinical syndromes linked to mutations in IKBKG." (PMID 35289316, 2022).
lymphoma (5 papers, 2014 to 2020). A malignant (clonal) proliferation of B- lymphocytes or T- lymphocytes which involves the lymph nodes, bone marrow and/or extranodal sites. "We tested this hypothesis in lymphomas because of our prior analysis showing that CYLD, IKBKB (encoding IKKβ), and IKBKG (encoding NEMO) are highly co-expressed in hemato-lymphoid cells." (PMID 32024820, 2020).
colorectal cancer (4 papers, 2022 to 2024). A primary or metastatic malignant neoplasm that affects the colon or rectum. "Interestingly, IKBKG inhibition suppresses the proliferation of colorectal cancer cells in vitro." (PMID 38051091, 2024).
lung carcinoma (4 papers, 2017 to 2025). "While these findings provide novel insights into the complex interplay between autophagy, splicing, and cancer, further studies are required to elucidate the precise mechanisms underlying the functional differences between IKBKG splice variants in the context of lung cancer." (PMID 39897555, 2025). "To comprehensively assess the clinical relevance of IKBKG splicing in lung cancer, we conducted an analysis of the TCGA dataset." (PMID 39897555, 2025). "Our results suggest that DDX24 modulates lung cancer cell proliferation by regulating IKBKG alternative splicing and subsequent autophagy induction." (PMID 39897555, 2025). "RT-PCR assay revealed a marked decrease of IKBKG-L (reduced PSI) in tumor tissues compared to normal tissues, suggesting a potential role for IKBKG alternative splicing in lung cancer progression." (PMID 39897555, 2025). "To validate these findings in a clinical setting, we analyzed IKBKG splicing in paired lung cancer and adjacent normal tissue samples." (PMID 39897555, 2025). "To investigate whether IKBKG-L-mediated autophagy is responsible for depleted DDX24-induced suppression of lung cancer progression, we generated lung cancer cell lines with concurrent knockdown of DDX24 and the long IKBKG isoform." (PMID 39897555, 2025).
neuroectodermal dysplasia (4 papers, 2023 to 2024). "IP is a rare neuroectodermal dysplasia caused by mutations in the IKBKG gene, located at Xq28." (PMID 39882206, 2024).
pancreatic cancer (4 papers, 2020 to 2024). "As in mice, high-IKBKG expression in pancreatic cancer patients correlated with longer survival, with a 37% 5-year survival for high-expression cases versus 23% for low-expression cases." (PMID 38755681, 2024).
preeclampsia (4 papers, 2017 to 2023). Preeclampsia is a hypertensive disorder of pregnancy that is characterized by new-onset hypertension with proteinuria presenting after 20 weeks of gestation, and depending on mild or severe forms may initially present with severe headache, visual disturbances, and hyperreflexia. "Future examinations should be conducted to determine how the IKBKG:c.*402C>T variant influences the development of preeclampsia." (PMID 28654673, 2017). "Our results showed that, the simultaneous occurrence of the maternal TT genotype (IKBKG:c.*402C>T variants) and TT genotype in the daughter or T allele in the son correlates with the level of NEMO gene expression and increases the risk of preeclampsia development." (PMID 28654673, 2017). "We suppose that the maternal/fetal carriage of IKBKG:c.*402T variant may be responsible for activating one of the numerous pathways of preeclampsia development." (PMID 28654673, 2017). "In summary, this is the first study to report an association between single nucleotide variant in NEMO gene (IKBKG:c.*402C>T) and the elevated risk of preeclampsia development." (PMID 28654673, 2017).
steatosis (4 papers, 2012 to 2021). Increased lipid within the cytoplasm of cells. "For example, deletion of NF-κB essential modifier (NEMO, also known as IKBKG) in liver parenchymal cells in mice impaired liver regeneration and spontaneously developed progressive NAFLD (that is, steatosis, NASH, and cirrhosis)." (PMID 33542919, 2021).
esophageal cancer (3 papers, 2020 to 2024). A primary or metastatic malignant neoplasm involving the esophagus. "Our findings reveal that IKBKB and IKBKG are significantly upregulated in all examined cancers, while CHUK is upregulated in esophageal carcinoma and stomach adenocarcinoma." (PMID 39337357, 2024).
Obesity (3 papers, 2013 to 2024). Accumulation of substantial excess body fat. "IKBKB and IKBKG genes were upregulated in patients with normal weight compared to those who were of extreme weight (p = 0.0287; 0.0083, respectively) or extreme obesity (p = 0.0006 for IKBKG)." (PMID 39337357, 2024).
small cell lung carcinoma (3 papers, 2022 to 2025). Small cell lung cancer (SCLC) is a highly aggressive malignant neoplasm, accounting for 10-15% of lung cancer cases, characterized byrapid growth, and early metastasis. "Since NF-κB is typically associated with the development of tumors, such as small cell lung cancer, rectal cancer, and multiple myeloma, some types of IKBKG mutations accompany tumors." (PMID 40612668, 2025).
epilepsy (2 papers, 2024 to 2025). A brain disorder characterized by episodes of abnormally increased neuronal discharge resulting in transient episodes of sensory or motor neurological dysfunction, or psychic dysfunction. "IKBKG produces an upregulation of NF-κB, a transcription factor that plays a critical role in epilepsy, since under normal conditions the transcription factor is retained in the cytoplasm by its inhibitor." (PMID 40076950, 2025). "IKBKB was also highly expressed in the epilepsy group, while IKBKG was higher only in the T. gondii‐positive groups." (PMID 39046369, 2024).
esophageal squamous cell carcinoma (2 papers, 2017 to 2024). Esophageal squamous cell carcinoma (ESCC) is a type of esophageal carcinoma (EC) that can affect any part of the esophagus, but is usually located in the upper or middle third. "Lower expression levels of CHUK, IKBKB, and IKBKG in stomach adenocarcinoma and IKBKB in esophageal squamous cell carcinoma correlate with shorter overall survival." (PMID 39337357, 2024).
Gaucher disease (2 papers, 2022 to 2023). Gaucher disease (GD) is a lysosomal storage disorder encompassing three main forms (types 1, 2 and 3), a fetal form and a variant with cardiac involvement (Gaucher disease - ophthalmoplegia - cardiovascular calcification or Gaucher-like disease). "Only one patient who had IKBKG exon 4–10 deletion additionally had an NGS and WES analysis-detected heterozygous GBA mutation responsible for Gaucher disease (OMIM * 606,463, ORPHA 355)." (PMID 37046518, 2023). "The methods used in diagnostics were as follows: IKBKG gene analysis, the X-chromosome inactivation assay, analyses of the genes relevant for neurodegeneration, WES analysis, analysis of biochemical parameters typical for Gaucher disease (GD), and autoantibodies including IFN-α2a and IFN-ω." (PMID 35885615, 2022).
Intellectual disability (2 papers, 2013 to 2025). "Clinical studies have reported that patients with increased copy numbers of IKBKG gene, which encodes NF-κB essential modulator (NEMO), exhibit reduced NF-κB signaling, accompanied by abnormal myelination, morphological abnormalities in the developing brain, and mild intellectual disability." (PMID 40766184, 2025). "Besides involvement of IKBKG gene mutation in mental retardation that is generally recognized, there are more than 290 other genes involved in mental retardation." (PMID 23406512, 2013).
osteoporosis (2 papers, 2020 to 2025). A condition of reduced bone mass, with decreased cortical thickness and a decrease in the number and size of the trabeculae of cancellous bone (but normal chemical composition), resulting in increased fracture incidence. "Further, in vivo and in vitro studies confirmed that OC-Exo-packaged miR-30a-3p was transferred to OBs and inhibited bone formation, possibly via targeting IKBKG to initiate caspase-1 activation and the secretion of IL-1β and IL-18, thus accelerating the progression of osteoporosis." (PMID 40110632, 2025).
renal carcinoma (2 papers, 2017 to 2023). A carcinoma arising from the epithelium of the renal parenchyma or the renal pelvis. "Subsequently, using the HPA database, we downloaded immunohistochemical images of IKBKG and IKBKB from normal and cancerous tissues and found that their expression of IKBKG and IKBKB in renal cancer tissues was higher than that in normal kidney tissues." (PMID 37847185, 2023).
squamous cell carcinoma (2 papers, 2022 to 2024). A carcinoma arising from squamous epithelial cells. "Conversely, for the IKBKG gene, higher expression was noted for the squamous cell carcinoma type of ESCA (p < 0.001)." (PMID 39337357, 2024).
acute liver failure (1 paper, 2024). Rapid deterioration of liver function causing encephalopathy and coagulopathy. "In APAP-induced acute liver failure patients (GSE74000), IKBKG levels decreased, and Nrf2 target genes were also repressed (i.e., HMOX1, PRDX1, TXNRD1, GPX4, GPX1, GCLC, GCLM, and NQO1)." (PMID 38505605, 2024).
bone marrow failure (1 paper, 2021). "Patients ID80 and ID260 carried pathogenic variants in the X-linked IKBKG and the CARD11 genes, respectively, showing a clinical overlap between IEI and bone marrow failure, in line with what was recently demonstrated." (PMID 34573280, 2021).
breast adenocarcinoma (1 paper, 2025). "Mutations in the NOD1/2 signaling pathway and in DNA binding transcription factor activity, affecting genes such as MAP3K7, UBE2N, IKBKG, CHUK, and IKBKB, occurred late in breast adenocarcinoma and ovarian adenocarcinoma." (PMID 39868264, 2025).
Cerebral ischemia (1 paper, 2025). Restriction of arterial blood supply to the brain associated with insufficient oxygenation to support the metabolic requirements of the tissue. "EVs regulate IKBKG through miR-125a-5p to inhibit the TLR4/NF-κB signaling pathway and exert neuroprotective effects against cerebral ischemia, emphasizing the critical role of miR-125a-5p in neuroinflammation and neuronal death after CIRI." (PMID 40585973, 2025).
colon adenocarcinoma (1 paper, 2024). "Conversely, in esophageal adenocarcinoma, reduced IKBKG expression is linked to longer overall survival, while higher IKBKB expression in colon adenocarcinoma is associated with longer overall survival." (PMID 39337357, 2024).
Erythema (1 paper, 2022). Redness of the skin, caused by hyperemia of the capillaries in the lower layers of the skin. "We here report a case of an IKBKG gene deletion in a female infant presenting with a few blisters and erythema in her upper arms at birth." (PMID 35768795, 2022).